H2AZ2 (H2A.Z variant histone 2)
Description:
Variant histone H2A which replaces conventional H2A in a subset of nucleosomes. Nucleosomes wrap and compact DNA into chromatin, limiting DNA accessibility to the cellular machineries which require DNA as a template. Histones thereby play a central role in transcription regulation, DNA repair, DNA replication and chromosomal stability. DNA accessibility is regulated via a complex set of post-translational modifications of histones, also called histone code, and nucleosome remodeling. May be involved in the formation of constitutive heterochromatin. May be required for chromosome segregation during cell division (By similarity).
Synonyms: H2AFV; H2AV; MGC10170; MGC10831; MGC1947; H2A.Z-2
Tractability: PROTAC: UniProt records ubiquitination sites on it; ubiquitination databases record sites on it.
Gene: Protein-coding gene on chromosome 7 (44,826,791 to 44,848,146, reverse strand). Ensembl gene ENSG00000105968.
Subcellular location: Nucleus; Chromosome
Pathways (Reactome):
Gene expression (Transcription): B-WICH complex positively regulates rRNA expression; DNA methylation; ERCC6 (CSB) and EHMT2 (G9a) positively regulate rRNA expression; MLL4 and MLL3 complexes regulate expression of PPARG target genes in adipogenesis and hepatic steatosis; NoRC negatively regulates rRNA expression; PRC2 methylates histones and DNA; RNA Polymerase I Promoter Escape; RNA Polymerase I Promoter Opening; RUNX1 regulates genes involved in megakaryocyte differentiation and platelet function; RUNX1 regulates transcription of genes involved in differentiation of HSCs; Regulation of endogenous retroelements by KRAB-ZFP proteins; Regulation of endogenous retroelements by Piwi-interacting RNAs (piRNAs); Regulation of endogenous retroelements by the Human Silencing Hub (HUSH) complex; SIRT1 negatively regulates rRNA expression; Transcriptional regulation by small RNAs
Chromatin organization: CHD1 and CHD2 subfamily; CHD6, CHD7, CHD8, CHD9 subfamily; ChAHP complex assembly; Interaction of NuRD complexes with transcription factors; NuRD complex assembly; RMTs methylate histone arginines
Cell Cycle: Condensation of Prophase Chromosomes; Deposition of new CENPA-containing nucleosomes at the centromere; Inhibition of DNA recombination at telomere; Packaging Of Telomere Ends
DNA Repair: Cleavage of the damaged purine; Cleavage of the damaged pyrimidine; Recognition and association of DNA glycosylase with site containing an affected purine; Recognition and association of DNA glycosylase with site containing an affected pyrimidine
Signal Transduction: Activated PKN1 stimulates transcription of AR (androgen receptor) regulated genes KLK2 and KLK3; Estrogen-dependent gene expression; Formation of the beta-catenin:TCF transactivating complex; Pre-NOTCH Transcription and Translation
Cellular responses to stimuli: DNA Damage/Telomere Stress Induced Senescence; Oxidative Stress Induced Senescence; Senescence-Associated Secretory Phenotype (SASP)
Developmental Biology: Activation of anterior HOX genes in hindbrain development during early embryogenesis; Chromatin modifications during the maternal to zygotic transition (MZT); Transcriptional regulation of granulopoiesis
Reproduction: Meiotic recombination
and 5 more pathways
Gene Ontology:
Molecular function: molecular adaptor activity; structural constituent of chromatin; DNA binding; protein heterodimerization activity
Biological process: chromatin organization; heterochromatin formation
Cellular component: extracellular exosome; nucleosome; nucleus; chromosome
Genetic constraint (gnomAD): Loss-of-function variants: 4 observed, 8.61 expected, observed/expected ratio (o/e) 0.46, 90% interval 0.23 to 1.06. That is too few expected variants to judge how well the gene tolerates losing a copy. Missense variants: 36 observed, 140.7 expected, observed/expected ratio (o/e) 0.26, 90% interval 0.19 to 0.34. Synonymous variants: 39 observed, 49.26 expected, observed/expected ratio (o/e) 0.79, 90% interval 0.61 to 1.03.
Homologues: Orthologues: chimpanzee H2AZ2 (100% identical), mouse H2az2 (100% identical), pig H2AZ2 (100% identical), zebrafish h2az2a (100% identical), chimpanzee H2AZ2 (99% identical), guinea pig H2AZ2 (99% identical), macaque H2AZ2 (99% identical), rat H2az2 (99% identical), rat H2az2l3 (99% identical), zebrafish h2az2b (98% identical), rat H2az2l2 (96% identical), Drosophila melanogaster His2Av (95% identical), and 3 more. Paralogues in human: H2AZ1 (98% identical), H2AC18 (63% identical), H2AC19 (63% identical), H2AC25 (63% identical), H2AC6 (63% identical), H2AC1 (62% identical), H2AC11 (62% identical), H2AC12 (62% identical), H2AC13 (62% identical), H2AC14 (62% identical), H2AC15 (62% identical), H2AC16 (62% identical), and 15 more.
Diseases named in the same sentence as H2AZ2 in open-access papers:
H2AZ2 is named in the same sentence as 17 diseases in open-access papers, as found by Europe PMC text mining. Sharing a sentence is not in itself a finding about the gene and the disease. The quoted sentences say what the papers report.
melanoma (4 papers, 2016 to 2022). A malignant, usually aggressive tumor composed of atypical, neoplastic melanocytes. "In melanoma, it was proposed that H2AZ2 exerts its oncogenic function by recruiting E2F1 and BRD2 to the promoters of cell cycle genes." (PMID 35058574, 2022).
glioma (1 paper, 2022). A benign or malignant brain and spinal cord tumor that arises from glial cells (astrocytes, oligodendrocytes, ependymal cells). "Finally, we highlight the intimate link between high STAT3 signaling, E2F1 and H2AZ2 expression in glioma patients." (PMID 35058574, 2022). "In glioma patients, high STAT3 signaling is associated with high E2F1 and H2AZ2 expression." (PMID 35058574, 2022). "To this end, we generated a query signature that comprised the low expression of H2AZ2-positively correlated genes and high expression of H2AZ2-negatively correlated genes in TCGA gliomas, and submitted this “anti-H2AZ2” gene signature to the Connectivity Map Analysis (CMA)." (PMID 35058574, 2022). "To strengthen the idea that H2AZ2 also regulates cell cycle genes in glioma patients, we subjected genes that positively correlated with H2AZ2 expression in gliomas to the ConsensusPathDB analysis, revealing an enrichment of the cell cycle pathway in both TCGA and REMBRANDT cohorts." (PMID 35058574, 2022). "Since the H2AZ1 and H2AZ2 isoforms share many similarities in their genome-wide occupancy and protein interactions, we speculate that both isoforms would regulate glioma proliferation." (PMID 35058574, 2022). "Given the lack of a H2AZ2-specific antibody to further substantiate the overexpression of H2AZ2 in GBM, we performed RNAscope analysis of H2AZ2 in glioma patient tumor microarray wherein each single dot represents a H2AZ2 transcript at single cell resolution." (PMID 35058574, 2022). "From our ATAC-Seq analysis of H2AZ2 KD cells, we searched the ReMap datasets and identified E2F4 among the top glioma-relevant transcriptional regulators whose promoter accessibility may be altered in H2AZ2 depleted cells." (PMID 35058574, 2022). "There was a significant association between H2AZ2 and E2F1 (but not E2F4), suggesting that E2F1 may be co-expressed with H2AZ2 in glioma." (PMID 35058574, 2022).
cancer (5 papers, 2016 to 2023). A tumor composed of atypical neoplastic, often pleomorphic cells that invade other tissues. "The molecular basis for H2AZ2 overexpression in cancer remains unclear." (PMID 35058574, 2022). "Notably, two distinct isoforms of H2AZ variant histone, namely H2AZ1 and H2AZ2 that are encoded by two non-allelic genes and differ only by three amino acids, are overexpressed in multiple cancers." (PMID 35058574, 2022).
tumor (3 papers, 2022 to 2024). "Extending these in vitro findings to xenotransplantation experiments, we showed that H2AZ2 depleted GSCs generated significantly smaller tumor volume than the H2AZ2 intact controls." (PMID 35058574, 2022). "Silencing H2AZ2 also significantly decreased GSC tumor initiating cell frequency as revealed by the extreme limiting dilution assay, which tracked with reduced FABP7 (a GSC marker) levels." (PMID 35058574, 2022). "However, specific genes within the BRCA dataset such as H2AZ2 (H2A histone family member V) and LRRFIP1 (leucine-rich repeat flightless-interacting protein 1) exhibited a significant increase in TR in most tumor samples compared to normal tissues." (PMID 39349823, 2024).
H2AZ2 also shares sentences with these, for which no sentence is quoted: hepatocellular carcinoma (2 papers); autism (1); bladder cancers (1); breast carcinoma (1); colorectal cancer (1); developmental delay (1); diabetes (1); head and neck squamous cell carcinoma (1); meningioma (1); metastatic melanoma (1); synovial sarcoma (1); systemic lupus erythematosus (1); viral infection (1).